MMP2 (matrix metallopeptidase 2)
Diseases named in the same sentence as MMP2 in open-access papers (continued):
Sharing a sentence is not in itself a finding about the gene and the disease.
tumor (continued). "Extracellular matrix degradation plays an important role in tumour invasion and metastases, which is mainly mediated by MMP2 and MMP939." (PMID 38816545, 2024). "A helical microrobotic swimmer composed of collagen was developed to exploit the high levels of MMP-2 in tumor tissues." (PMID 39125066, 2024). "Apart from neutrophils, the tumour associated macrophages and other leukocytes have been related with aggressive tumour behaviour of invasion and metastasis through MMP-2 by inducing extracellular matrix remodeling." (PMID 38616289, 2024). "Aberrant FCRLA expression can promote malignant biological behaviors of RCC, with suppression of tumor cell apoptosis in an MMP2‐dependent manner." (PMID 39108036, 2024). "It was shown that the most common MMPs in PDAC are MMP1, MMP14, and MMP2, which are secreted by epithelial tumor cells, M2-like macrophages, and fibroblastic cells." (PMID 39338413, 2024). "The DSF released from PFP@PDM-PEG reduced VM formation by inhibiting COL1 expression, thereby affecting pro-MMP-2 activation, which further inhibited tumor growth and distant metastasis." (PMID 38664830, 2024). "This study involved 90 CRC patients, with tumor and adjacent normal tissues analyzed via immunohistochemistry (IHC) to assess MMP2 expression." (PMID 38978899, 2024). "Elevated expression of MMP1, MMP2, MMP3, MMP7, MMP9, MMP13, and MMP14 has been consistently associated with tumor progression, metastasis, and a less favorable prognosis." (PMID 38939095, 2024). "In HCT 116 and SW480 cells transfected with miR-497 mimics, the levels of the tumor invasion markers MMP-2 and MMP-9 proteins were significantly reduced compared to control cells via targeting Fra-1, demonstrating that miR-497 inhibits invasion in these cells." (PMID 39858430, 2024). "Due to the elevated concentration of MMP-2 around the tumor, this promotes rapid swelling of the hydrogel network, which facilitates drug release." (PMID 38675303, 2024). "We also considered the potential cross-reactivity of the MMP-11 antibody with other MMPs, such as MMP2 (gelatinase A), MMP9 (gelatinase B), and MMP14 (membrane-type 1 MMP), which are commonly associated with tumor cells." (PMID 38438841, 2024). "NFATC1 increase BLCA to promote tumor cell growth/colony formation, and can also promote tumor migration and invasion by providing the expression of MMP2 and MMP9." (PMID 38910160, 2024). "Tumor weight reduction was observed in a dose-dependent manner, and immunohistochemical staining revealed fewer Ki67-positive and MMP-2-positive cells in tumors treated with hinokiflavone compared to the control group." (PMID 39065725, 2024). "Evidence has indicated that MMP‐2 and ‐9 are upregulated in OC and both MMPs play key roles in the migration of tumor cells." (PMID 38531560, 2024). "These nanocarriers accumulate in the tumor and, under the influence of MMP2, release the drug‐bearing dendrigraft, reaching a high depth of the tumor." (PMID 39217459, 2024). "The inhibition of COL1, in turn, hampers the activation of pro-MMP-2, thereby disrupting VM, a critical factor in tumor growth and metastasis." (PMID 38664830, 2024). "In particular, MMP2 is involved in the migration through collagen type I, which is present in the core of the tumor and the perivascular space." (PMID 38473812, 2024). "This secure and controllable dual-response DSF delivery platform reduced VM formation by inhibiting COL1/pro-MMP-2 activity, thereby significantly inhibiting tumor progression and metastasis." (PMID 38664830, 2024). "MMP2 and MMP17 have been implicated in extracellular matrix (ECM) degradation, angiogenesis, and the facilitation of tumor cell migration and invasion, which contribute to disease progression and poor patient outcomes." (PMID 39062041, 2024).
tumor (continued). "Although our data are interesting, further studies need to be performed to correlate levels of MMP2 with age, histotype, grade, tumor size, and stage." (PMID 38731868, 2024). "This molecule can promote EMT to participate in tumor cell migration and invasion by upregulating MMP2, MMP9 and other factors and can directly activate VEGF and HIF-1α to promote tumor angiogenesis and other aspects to promote tumor metastasis." (PMID 38486162, 2024). "An additional critical role of TGF-β is the function it plays in promoting tumor invasion by upregulating matrix metalloprotein (MMP)-2, a protein shown to play important roles in neo-angiogenesis and tumor vascularization." (PMID 38893093, 2024). "Researchers have also found that altering MMP-9 and MMP-2 expression leads to increased activity and tumor aggressiveness." (PMID 39769318, 2024). "In many cancers, tumor cells use matrix metalloproteinase-2 (MMP-2) enzymes to escape from the surrounding stroma; thus, local concentrations of MMP-2 are elevated." (PMID 38675303, 2024). "Some researchers have observed increased MMP-2 expression in the stroma of high-risk BCC subtypes compared to low-risk subtypes, indicating a potential role in tumor invasiveness." (PMID 39525230, 2024). "Consistently, the results of Western blotting assay revealed that TIM3-mimic group had notably higher protein expressions of tumor invasion and metastasis-related molecules, matrix metalloproteinase-2 (MMP-2) and MMP-9 in TC cells than TIM3-NC group." (PMID 38568917, 2024). "In the therapeutic process, the ENP919@5-FU nanovesicle was easily accumulated in tumor tissue by high expression MMP-2 enzymes, effectively enhancing tumor cellular uptake." (PMID 38755645, 2024). "Up to 88% reduction in tumor volume with human MMP-2 oligopeptide; 80% reduction with one of the human MMP-9 oligopeptides; no pronounced side effects." (PMID 39594665, 2024). "MMP-2 is secreted by tumor cells to degrade collagen, the main component of the extracellular matrix, facilitating escape from the primary tumor site and promoting metastasis." (PMID 39125066, 2024). "Previous studies have reported that 37LRP plays an important role in tumor invasion and metastasis and that 37LRP is regulated by pJNK and can promote the secretion of many proteolytic enzymes, including MMP2, by binding to laminin to change its conformation." (PMID 38678020, 2024). "The IHC experiment results showed that the expression of TWIST1 and MMP2 was significantly increased in tumor stage lesion of MF, indicating an increasing level of EMT and CAF-related matrix remodeling." (PMID 39963655, 2024). "Single-cell analysis revealed high expression of SPHK1 in tumor cells (SOX2, KRT18) and cancer-associated fibroblasts (COL1A2 and MMP2) and low expression in cancer stem cells (PROM1)." (PMID 39629135, 2024). "It targets matrix metalloproteinase-2 (MMP2), an enzyme involved in degrading the extracellular matrix, which facilitates tumor invasion and metastasis." (PMID 39594601, 2024). "Overexpression of miR-29c-3p in exosomes produced from CAF suppresses tumor metastasis by amplifying its impact on the direct target, matrix metalloproteinase 2 (MMP2)." (PMID 38694824, 2024). "The short peptide sequence PLGLAG is an MMP2/MMP9-sensitive linking fragment that can be cleaved in tumor tissue." (PMID 38429828, 2024). "MMP-2 facilitates tumor invasion and metastasis by degrading basement membrane components, enabling cancer cell migration and tube formation, critical for neovascularization in tumors." (PMID 39769454, 2024). "Because of their sensitivty to changes in MMP-2 concentration and redox potential, the NPs achieved multi-responsive drug delivery to the tumor microenvironment and showed excellent anti-cancer efficacy in further in vitro and in vivo experiments." (PMID 38910887, 2024).
tumor (continued). "When the tumor cells are transfected with IL-8, it results in the upregulation of MMP-2 mRNA levels while VEGF and bFGF mRNA levels remain unchanged." (PMID 38672182, 2024). "Elevated MMP-2 and MMP-9 activity is closely linked to the formation of metastatic niches, angiogenesis, and other functions within the tumor microenvironment, such as the chemotaxis of inflammatory cells and the perpetuation of an inflammatory milieu." (PMID 39684484, 2024). "MMP-2 is a kind of secreted protein that exists in the extracellular matrix and is involved in tumor invasion, and is therefore a target of anti-tumor drugs." (PMID 38755645, 2024). "Activated cell-penetrating peptides (ACPPs), which target the matrix metalloproteinase (MMP)-2 enzymes, increase tumour uptake and contrast imaging in in vivo tumour necrosis models when covalently attached to cyclic-RGD peptide." (PMID 39720730, 2024). "In terms of upregulated DEGs, seven genes (ABI3BP, CTSG, DPP4, CCL18, OSR2, GRIA3, MMP2) demonstrated reduced expression in tumor compared to normal tissue." (PMID 39062832, 2024). "The extremely high concentration of ATP in extracellular TME not only promotes tumor cell extravasation and detachment from the primary site but also stimulates tumor cells and stromal cells to release matrix metalloproteinases (MMPs), such as MMP2/9." (PMID 38202850, 2024). "An immunohistochemical assay showed a dose-dependent reduction in MMP-2 expression in tumor sections." (PMID 39335164, 2024). "The amount of extracellular matrix is primarily regulated by MMPs and tissue inhibitors of metalloproteinase, with MMP2 shown to be involved in tumor development." (PMID 39108036, 2024). "Subsequently, we performed IHC staining analysis of VM-related markers, including VM markers VE-cadherin, Fibronectin 1 (FN1), SERPINE2, tumor microenvironment markers MMP2 and MMP9, epithelial cell marker E-cadherin and mesenchymal cell marker vimentin." (PMID 38164156, 2024). "For tumor-targeted delivery, we employed an MMP-2/9-sensitive scaffold that cloaks polycationic cell-penetrating peptide–drug conjugates in an inaccessible state." (PMID 39683778, 2024). "The percentages of lymphoid-based MMP4 and MMP2 cells were the same in both groups and at both time points post tumor implantation." (PMID 38457336, 2024). "PRTN3 promotes the activation of matrix metalloproteinases (MMP)-2, which are involved in angiogenesis and tumor invasion." (PMID 38308214, 2024). "This tailored response to MMP-2 not only facilitates cellular drug uptake but also optimizes drug distribution within the tumor." (PMID 38664830, 2024). "For example, PEG-PLA bridged with a synthetic polypeptide PVGLIG sensitive to matrix metalloproteinase 2 (MMP2) overexpressed in tumor extracellular matrix exhibited a seven-fold increase in SN38 release compared to the control formulation." (PMID 38255485, 2024). "Due to the dual nature of TIMP-2, small shifts in the MMP-2/TIMP-2 balance can facilitate tumour progression and influence disease recurrence." (PMID 37932474, 2023). "They showed superior targeting capacities with TPP1 peptide being delivered and released to the tumor microenvironment through the homotypic effect of tumor cell membrane and specific digestion by the tumor-specific enzyme MMP2." (PMID 36678868, 2023). "More importantly, the ΔR1 of different tumours were calculated, and the real MMP‐2 content of these tumour tissues were also detected by western blot analysis." (PMID 38264683, 2023). "PTEN expression not only affects cellular proliferation and growth, but the tumor suppressor also inhibits migration via suppressing effects on various MMPs, including MMP2 and MMP9." (PMID 37313172, 2023). "Since the majority of produced VEGF is sequestered in the ECM deposited by tumor and stromal cells, the proteolytic release of angiogenic factors from tissue matrix, mainly mediated by MMP-2 and MMP-9, is essential for in vivo induced angiogenesis." (PMID 36759828, 2023).
tumor (continued). "At the tumor site, MMP-2 cutting occurs and a positively charged histidine micelle with paclitaxel penetrates deeper inside the tumor tissue." (PMID 36678860, 2023). "CD147 enrichment on the surface of tumor cells is an important regulator of tumor mesenchymal interactions, as it stimulates the neighboring mesenchyme to promote synthesis of several MMPs (mainly MMP-2,9)." (PMID 37090718, 2023). "MGF causes downregulation of matrix metallopeptidase 2 (MMP‐2) and matrix metallopeptidase 9 (MMP‐9), which result in decreased cellular proliferation (progression) and tumor motility; these processes ultimately lead to an increase in body weight." (PMID 38455223, 2023). "The micelles are passively delivered to the tumor tissues and ensure the controlled release of both drugs in response to the enriched MMP-2 expression in the TME." (PMID 36986532, 2023). "AGEs caused an increase in pERK and MEK1/2 inhibitor-induced reduction of this phosphorylation led to suppression of the Sp1 expression, suggesting the involvement of the RAGE/ERK/Sp1/MMP2 pathway in AGE-induced tumor invasion and metastasis." (PMID 36677584, 2023). "The degradation of type IV collagen, the major structural collagen of the extracellular matrix, by MMP-2 and/or MMP-9, is often associated with tumor invasion and metastasis." (PMID 37057283, 2023). "Remodeling of tumor cells and the extracellular matrix to provide space for tumor cell deformation and motility is a major factor in VM formation, and MMP2 plays a key role in this process." (PMID 37217473, 2023). "Self-assembling into fiber nanostructures with surface targeting moieties was obtained, which upon cleavage of the MMP2 in the tumor environment, turned to micelles presenting CPP at their surface to facilitate cell penetration across the cell membrane." (PMID 37896241, 2023). "Here, we designed a smart transformable peptide‐conjugated probe (DMFA) capable of undergoing morphological conversion cleaved by pericellular overexpressed matrix metalloproteinase‐2 (MMP‐2) to achieve high toxicity and metastasis inhibition on tumor cells." (PMID 36793151, 2023). "The statistical analysis did not confirm the presence of the correlation between the expression of TIMP1 (p = 0.4306), MMP2 (p = 0.9208) or MMP9 (p = 0.8674) in blood before surgical removal of tumor tissue and survival of patients with NSCLC." (PMID 37509417, 2023). "MMP-2 overexpressed outside of the tumor cells catalyzes the degradation of the gelatin layer exposing the hyaluronic acid coating, which acts both as a targeting and capping agent." (PMID 36839771, 2023). "The internalization efficiency of P‐aPD‐L1/C at pH 6.5+10 × 10−9m MMP‐2 (up to 99.8%) was significantly higher than that at pH 7.4 (only 14.6%), indicating the excellent tumor targeting of P‐aPD‐L1/C." (PMID 36437106, 2023). "It acts as a tumour suppressor in both types of cancer, as it can suppress the secretion of MMP-2 and MMP-9." (PMID 36982551, 2023). "MMP2/9 secretion, migration, invasion, and colonization of tumor cells are stimulated by COL4A1 through activation of the PI3K/AKT signaling pathway and DDRs." (PMID 38004422, 2023). "Further, major MMPs involved in promoting tumor angiogenesis, which is an important step for tumor vascularization and also represents an avenue for metastasis, include MMP-2, MMP-9 and MMP-14." (PMID 37091337, 2023). "Taken together, these data showed that mouse cardiac-specific expression of Cre recombinase leads to development of tumor-like lesions in the atrium, along with strong significant upregulation of MMP-2 and MMP-9 after six months of age." (PMID 36834504, 2023). "After the system binds to GLUT1 on tumor cells, the MMP2-sensitive peptide linker was disrupted, and the PEG layer separated from PAMAM." (PMID 36986532, 2023).
tumor (continued). "On the other hand, MMP-2-positive staining was only found in the tumor-like cells (enlarged photograph of black frame) and their staining densities were lighter than those of the areas of MMP-9-positive staining." (PMID 37175975, 2023). "In our study, treatment with MMP2 inhibitor alone significantly reduced tumor growth, while the combination of MMP2 inhibitor and anti-PD-1 antibody has a synergistic efficacy." (PMID 36788565, 2023). "SCRN1 accelerates tumor progression by the regulation of exocytosis of matrix metalloproteinase-2/9 (MMP-2/9), while RSPO3 is an oncogenic driver that causes CRC and extensive crypt hyperplasia, concomitantly stimulating stem cells and supportive niche cells." (PMID 37228491, 2023). "MMP-2 was found to be highly expressed in almost all tissue samples, not only in tumor cells (mostly), but also in inflammatory cells, endothelial cells, MVP, and necrotic areas." (PMID 37190125, 2023). "CAF expression of MMP11, MMP2, MMP9, and MMP21 in various malignancies is associated with a significant risk of tumor relapse." (PMID 38035101, 2023). "XH significantly reduced the expression of MMP-2 and MMP-9, strongly associated with the metastatic potential of many tumor cells." (PMID 37373500, 2023). "MMP-2 is well known for degrading ECM as well as being a tumor marker for head and neck cancer with a bad prognosis." (PMID 37228582, 2023). "The conclusion of the study is that octreotide inhibits the invasion and migration of SGC-7901 gastric cancer cells in vitro and reduces tumor metastasis in vivo by inhibiting MMP-2 expression and reducing tumor angiogenesis." (PMID 38201544, 2023). "The mechanistic insights revealed the silencing of AEG-1 and regulation of pivotal proteins, MMP-2/9, which are inherently involved in tumor progression." (PMID 38140058, 2023). "The collagenase matrix metalloproteinase 2 (MMP2) facilitates tumor growth and invasion by degrading the tumor tissue's extracellular matrix." (PMID 36700237, 2023). "A different study demonstrated that overexpression of p16 suppresses tumor cell invasion by reducing matrix metalloproteinase 2 (MMP-2)." (PMID 36831218, 2023). "β-CD and liposomes were linked by a metalloproteinase (MMP-2)-responsive peptide, and sequential release of SB-3CT and dihydroporphine e6 was induced by the MMP-2-enriched tumor microenvironment and 660 nm laser irradiation, respectively." (PMID 37513483, 2023). "Upon accumulation in theTME, the MMP-2-triggered release of iRGD facilitated the deep penetrationof nanomedicines in tumor tissues." (PMID 37901179, 2023). "While reaching the tumor site, MMP-2 degrades gelatin from 178 nm GND to release smaller 4 nm nanochitosan/doxorubicin (ND) nanoparticles for deep tumor penetration and efficient tumor cell endocytosis." (PMID 36926304, 2023). "To further verify that MMP2 inhibitor limited CAFs infiltration, we collected tumor tissues to study the tumor microenvironment of B16F10 tumor-bearing mice treated with MMP2 inhibitor and anti-PD-1 antibody combined or alone." (PMID 36788565, 2023). "TIMP2 is a known inhibitor of MMP activity and tumor growth that has been shown to be reciprocally downregulated with MMP2 upregulation." (PMID 36765529, 2023). "The RECK gene has been reported to encode a membrane-anchored glycoprotein that can negatively regulate MMP-2 and MMP-9 activities and is strongly associated with tumor angiogenesis and metastasis in various human cancers." (PMID 36895489, 2023). "Redox and MMP-2-responsive gelatin nanoparticles were developed for the delivery of paclitaxel (PTX) by utilizing glutathion (GSH) and MMP-2 that is over-expressed around some tumor tissues." (PMID 36850121, 2023).